ITGA2 (integrin subunit alpha 2)
Diseases named in the same sentence as ITGA2 in open-access papers (continued):
Sharing a sentence is not in itself a finding about the gene and the disease.
pancreatic cancer (34 papers, 2012 to 2025). "High expression of ITGA2 is associated with poor prognosis in pancreatic cancer patients, and the mechanism involves the upregulation of PD-L1 and remodeling of the immune microenvironment." (PMID 40940943, 2025). "ITGA2, E-cad and PD-L1 have been found to be associated with pancreatic cancer tumor markers CA19-9 and lymph node metastasis." (PMID 37881431, 2023). "Our previous research and recent local and foreign reports confirmed that the ITGA2 overexpression in pancreatic cancer is caused by the mutation and abnormal activation of KRAS." (PMID 35193647, 2022). "The transcriptional co-activators yes-associated protein (YAP) was considered as oncogene in many types of cancer; ITGA2 stimulating YAP activity was associated with unfavorable survival of pancreatic cancer patients." (PMID 30428899, 2018). "Additionally, we found that increased expression of ITGA2 is associated with a poor prognosis in pancreatic cancer patients." (PMID 37881431, 2023). "Thus, we reviewed previous studies and unexpectedly found that ITGA2 overexpression was associated with the most common KRAS mutation in pancreatic cancer." (PMID 35193647, 2022). "Interestingly, the host genes around this upstream interaction site were largely down-regulated, especially the ITGA2 gene, which has actually been found over-expressed in certain breast and pancreatic cancers causing increased cancer stemness and metastasis." (PMID 34432858, 2021). "In addition, epigenetic modifications such as DNA methylation were also important in tumorigenesis, and hypomethylation of ITGA2 with high gene expression was associated with poor survival in pancreatic cancer patients." (PMID 30428899, 2018). "It was reported that silencing of ITGA2 strengthened TGF-β’s ability to suppress pancreatic cancer cell proliferation and tumor growth." (PMID 41008552, 2025). "Previous studies have reported that ITGA2 is closely related to chemotherapy sensitivity and that its high expression mediates gemcitabine resistance in pancreatic cancer, 5-FU resistance in colorectal cancer, and 5-FU and ADR resistance in gastric cancer." (PMID 40940943, 2025). "The study included clinicopathological data of pancreatic cancer and the expression of ITGA2, CD4+T and CD8+T cells in tumor tissues for Cox model analysis." (PMID 37881431, 2023). "Our study discovered that the expression of CD4+ and CD8+ T cells in pancreatic cancer tissues was significantly reduced, while the expression of ITGA2 was increased." (PMID 37881431, 2023). "Blocking ITGA2 inhibited the proliferation and invasion ability of pancreatic cancer cells significantly, Additionally, sh-ITGA2 can down-regulate the expression of EMT and PD-L1." (PMID 37881431, 2023). "Pancreatic cancer exhibits high expression of ITGA2, however, the expression of CD4 and CD8 gradually decreases with tumor progression, rendering immunotherapy for advanced pancreatic cancer ineffective." (PMID 37881431, 2023). "Because ITGA2 is critical for promoting pancreatic cancer cell progression, we employed sh-ITGA2 to explore the relationship with EMT and PD-L." (PMID 37881431, 2023). "This indicates that ITGA2 not only contributes to the development of pancreatic cancer, but also has an immunosuppressive effect in the tumor immune microenvironment, which further promotes the progression of pancreatic cancer." (PMID 37881431, 2023). "Considering the relationship between aging, invasion, and metastasis of pancreatic cancer, it is crucial to consider ITGA2 mutation as significant as CDKN2A, BRCA1/2, and PALB2 mutations in the diagnosis and treatment of pancreatic cancer." (PMID 37881431, 2023). "In our study, we observed the expression of ITGA2, E-cad, and PD-L1 in both tumor tissues and stroma of patients with pancreatic cancer." (PMID 37881431, 2023). "In our study, we observed the expression of ITGA2, E-cadherin, and PD-L1 in both tumor and stroma tissues of pancreatic cancer." (PMID 37881431, 2023).
pancreatic cancer (continued). "ITGA2 involvement in “stiff” cancers, such as breast, prostate, colon and pancreatic cancer, has been extensively studied." (PMID 36765586, 2023). "In the study analyzing 62 postoperative specimens of pancreatic cancer, it was found that, on average, the density of ITGA2+ cells was expressed in 79.156% of pancreatic cancer tissues." (PMID 37881431, 2023). "The present study indicated that ITGA2, ITGA3, ADAM9, and BHLHE40 were potential target genes associated with the development of pancreatic cancer." (PMID 37377917, 2023). "This study evaluated the overall survival (OS) of pancreatic cancer patients by analyzing the expression of ITGA2, CD4, and CD8." (PMID 37881431, 2023). "Functional assays, such as the cell migration assay and transwell assay, were used to determine the biological role of ITGA2 in pancreatic cancer." (PMID 37881431, 2023). "In our study, we examined the expression profile of ITGA2 in pancreatic cancer and found that it was present in the majority of patients, particularly in those with moderately and poorly differentiated tumors." (PMID 37881431, 2023). "To investigate the effect of ITGA2 on the immune microenvironment of pancreatic cancer, we conducted immunohistochemistry to detect the expression of ITGA2, CD4+T cells, and CD8+T cells in tumor tissues." (PMID 37881431, 2023). "The results obtained in pancreatic cancer patients indicated high expression of ITGA2, E-cadherin, and PD-L1 in both the tumor and stroma." (PMID 37881431, 2023). "While ITGA2 has been shown to promote cancer in a variety of tumors, its role in immune regulation within the tumor microenvironment of pancreatic cancer has yet to be confirmed." (PMID 37881431, 2023). "We identified a novel mechanism in which ITGA2 plays a crucial role in the regulation of pancreatic cancer growth and invasion." (PMID 37881431, 2023). "The RT-PCR and Western blot analysis showed that the ITGA2 expression was significantly inhibited in the pancreatic cancer cells treated with KRASG12D or ERK1/2 inhibitors." (PMID 35193647, 2022). "Meanwhile, the protein expression levels of SMAD2, SMAD3, SMAD4, and p-SMAD2/3 were also detected in the pancreatic cancer cells with the ITGA2 gene silenced." (PMID 35193647, 2022). "In order to explore the accuracy of this conclusion and the regulatory mechanism of KRAS on ITGA2, the plasmid was transfected into the pancreatic cancer cell lines to overexpress KRASG12D." (PMID 35193647, 2022). "Taken together, these findings indicated that the ITGA2 silencing induced the SMAD2 expression in pancreatic cancer cells." (PMID 35193647, 2022). "In order to further study the regulatory mechanism of ITGA2 expression on the progression of pancreatic cancer cells, the previous RNA-sequencing data was reanalyzed and identified 427 upregulated and 365 downregulated DEGs." (PMID 35193647, 2022). "The results of the present study show that the abnormal activation of KRAS induced the overexpression of ITGA2 in pancreatic cancer." (PMID 35193647, 2022). "The effect of the ITGA2 inhibitor was evaluated in vivo by using a KrasG12D-driven murine pancreatic cancer model." (PMID 35719923, 2022). "Previous studies reported that the carcinogenic mechanism of ITGA2 is rarely involved in pancreatic cancer, except that blocking ITGA2 can improve tumor immune response by reducing the phosphorylation level of STAT3 and inhibiting the PD-L1 expression." (PMID 35193647, 2022). "ITGA2 silencing enhanced the anti-pancreatic cancer proliferation and tumor growth effects of TGF-β." (PMID 35193647, 2022). "Our previous study showed that ITGA2 was overexpressed in pancreatic cancer and promoted its progression." (PMID 35193647, 2022). "Recent studies on cancer tissues suggest that ITGA2 is related to the invasiveness of gastric and pancreatic cancer cells." (PMID 35017627, 2022).
pancreatic cancer (continued). "Previous studies showed that ITGA2 is overexpressed in tumor cells and related to the poor prognosis of patients with cancer, especially pancreatic cancer." (PMID 35193647, 2022). "We further analyzed the overall survival of COL3A1, FN1 and ITGA2 in pancreatic cancer and normal tissues." (PMID 34461940, 2021). "The protein expression of hub genes was higher in pancreatic cancer tissue than in normal pancreatic tissue samples, wherein ITGA2, LAMB3, and LAMC2 were exclusively expressed in pancreatic cancer cells." (PMID 34007003, 2021). "The increased ITGA2 expression promotes pancreatic cancer cell migration, invasion, metastasis, and chemoresistance." (PMID 34007003, 2021). "The increased ITGA2 level was reported in pancreatic cancer and others, including gastric, liver, prostate, and breast cancer." (PMID 34007003, 2021). "ITGA2 has been reported to play a critical role in modulating the pancreatic cancer immune response by transcriptionally increasing the expression of PD-L1 in cancer cells." (PMID 34567847, 2021). "One study found that the level of ITGA2 promoter methylation in pancreatic cancer reduced, resulting in elevated ITGA2 expression, but we cannot vouch for that observation here." (PMID 32202508, 2020). "A recent study has shown that ITGA2 increases the expression of PD-L1 by activating the STAT3 pathway in pancreatic cancer." (PMID 32899691, 2020). "The GEPIA web tool was used to find the clinical relevance of ITGA2 in cancer, and this significance was verified using Western blotting analysis of paired patient tissues and immunohistochemistry of the pancreatic cancer tissue." (PMID 31818309, 2019). "Given that ITGA2 levels regulated the progression of cancer cells in vitro, we studied the tumor-growth-promoting effect of ITGA2 in pancreatic cancer in vivo." (PMID 31818309, 2019). "However, studies on ITGA2 in GC, pancreatic cancer, HCC, CRC and other gastrointestinal tumors are gradually increasing." (PMID 39568561, 2024). "Although previous studies have demonstrated the significant roles of PD-L1 and EMT in pancreatic cancer, it remains unclear whether ITGA2 can regulate these factors." (PMID 37881431, 2023). "Our findings suggest that targeting ITGA2 could potentially be an effective approach to improve the effectiveness of checkpoint immunotherapy and inhibit the progression of pancreatic cancer." (PMID 37881431, 2023). "Therefore, targeting ITGA2 is an effective method to enhance the efficacy of checkpoint immunotherapy and prohibiting tumor growth against pancreatic cancer." (PMID 37881431, 2023). "Since ITGA2 is highly expressed in pancreatic cancer tissues and is considered as a biomarker gene for poor prognosis of pancreatic cancer, we aimed to further investigate its biological role in pancreatic cancer." (PMID 37881431, 2023). "Moreover, we observed that the significance of ITGA2 in pancreatic cancer was influenced by factors such as lymph node status, degree of differentiation, and local invasion status." (PMID 37881431, 2023). "The regulation of EMT by ITGA2 plays a crucial role in the growth of pancreatic cancer." (PMID 37881431, 2023). "ITGA2 can serve as a novel target for both the development and treatment of pancreatic cancer." (PMID 37881431, 2023). "Additionally, our findings point to ITGA2 acting as an oncogenic protein to promote the progression of pancreatic cancer." (PMID 37881431, 2023). "Additionally, ITGA2 also regulates the expression of PD-L1 in pancreatic cancer, which leads to changes in the immune microenvironment and further promotes the progression and metastasis of the cancer." (PMID 37881431, 2023). "Therefore, targeting ITGA2 is a promising approach to improve the effectiveness of checkpoint immunotherapy and inhibit tumor growth in pancreatic cancer." (PMID 37881431, 2023).
pancreatic cancer (continued). "Therefore, understanding the role of ITGA2 in these processes is of great significance in the development of effective treatments for pancreatic cancer." (PMID 37881431, 2023). "At first, we demonstrated that ITGA2 high expressed in several pancreatic cancer cells and knocking down ITGA2 inhibited pancreatic cancer cell proliferation and invasion suggesting that ITGA2 might play an essential role in the pathogenesis of PDAC." (PMID 37881431, 2023). "Taken together, these results indicated that ITGA2 expression could inhibit the activation of the TGF-β signaling pathway in pancreatic cancer via the TFCP2-SMAD2 axis." (PMID 35193647, 2022). "However, searching the GEPIA database showed that the mRNA expression levels of TFCP2 positively correlated with the mRNA expression levels of ITGA2 in the pancreatic cancer cells." (PMID 35193647, 2022). "The GEPIA database was used to confirm the expression of ITGA2 in pancreatic cancer." (PMID 35193647, 2022). "Taken together, these results indicated that the ITGA2 could inhibit the SMAD2 expression by interacting with TFCP2 in the pancreatic cancer cells." (PMID 35193647, 2022). "Besides, the biological functions of these proteins were detected using the colony formation assay and CCK8 cell proliferation assay in pancreatic cancer cells with ITGA2 and/or SMAD2 genes silenced." (PMID 35193647, 2022). "Thus, ITGA2 overexpression can further inhibit the TGF-β pathway to promote the proliferation of pancreatic cancer cells." (PMID 35193647, 2022). "Although our previous studies showed that overexpressed ITGA2 can upregulate PD-L1 to activate the STAT3 signaling pathway and thereby promote tumor cell progression, the carcinogenic mechanism of ITGA2 in pancreatic cancer still needs elucidation in further research." (PMID 35193647, 2022). "However, the mechanism of ITGA2 overexpression and other mechanisms for promoting the progression of pancreatic cancer are still unclear." (PMID 35193647, 2022). "Therefore, the purpose of this study was to examine other ways thereby ITGA2 regulates the progression of pancreatic cancer." (PMID 35193647, 2022). "The CCK-8 cell proliferation and colony formation assay showed that the ITGA2 silencing significantly could inhibit the proliferation ability of pancreatic cancer cells." (PMID 35193647, 2022). "Therefore, it was concluded that the ITGA2 silencing enhanced the anti-pancreatic cancer cell proliferation effect of TGF-β." (PMID 35193647, 2022). "The present study previously found that the ITGA2 could inhibit the SMAD2 expression by interacting with TFCP2 in the pancreatic cancer cells." (PMID 35193647, 2022). "Considering that ITGA2 silencing activated the TGF-β signaling pathway in pancreatic cancer cells, it was hypothesized that the ITGA2 silencing might enhance the anti-pancreatic cancer cell proliferation effect of TGF-β." (PMID 35193647, 2022). "In addition, the protein levels of COL3A1, FN1 and ITGA2 in pancreatic cancer were improved according to HPA." (PMID 34461940, 2021). "Although the exact mechanism by which ITGA2 is involved in pancreatic carcinogenesis remains unclear, it has been suggested that ITGA2 promotes pancreatic cancer progression through ECM remodeling." (PMID 34007003, 2021). "ITGA2 is highly expressed in GC, liver cancer, and pancreatic cancer." (PMID 33335550, 2020). "Our results here demonstrate that the increased expression of ITGA2 in ovarian cancer promoted the malignant biological behavior of tumor cells, which is consistent with findings in studies on pancreatic cancer, liver cancer, Hodgkin lymphoma, and osteosarcoma." (PMID 32202508, 2020). "Additionally, the RNA-seq assay indicated that ITGA2 transcriptionally regulated the expression of PD-L1 in pancreatic cancer." (PMID 31818309, 2019). "Additionally, our findings point to ITGA2 acting as an oncogenic protein to promote the progression of solid cancer, especially pancreatic cancer." (PMID 31818309, 2019).
pancreatic cancer (continued). "These two hub genes, ITGA2 and MMP7, may act as potential diagnostic and therapeutic biomarkers in pancreatic cancer patients." (PMID 30428899, 2018). "Results from the univariate analysis revealed that the expression of ITGA2+ cells was significantly associated with overall survival time, as well as the expression of CD4+ and CD8+T cells, degree of tissue differentiation, TNM stage, lymphatic metastasis, and local invasion in pancreatic cancer." (PMID 37881431, 2023). "Therefore, it was supposed that the ITGA2 could inhibit the SMAD2 expression via TFCP2 in the pancreatic cancer cells." (PMID 35193647, 2022). "Therefore, our findings indicate that ITGA2 might become a new therapeutic target for pancreatic cancer, especially when combined with TGF-β treatment." (PMID 35193647, 2022). "Therefore, TFCP2 might transcriptionally induce the ITGA2 expression by acting as a transcription factor in the pancreatic cancer cells." (PMID 35193647, 2022). "Also, the expression level of ITGA2 increases in pancreatic cancer due to promoter hypomethylation." (PMID 32202508, 2020). "MiR-216a is involved in the progression of pancreatic cancer through the two-axis, including miR-216a/tetraspanin-1 (TSPAN1)/integrin alpha-2 precursor (ITGA2) and LINC01133/miR-216a-5p/translationally-controlled tumor protein (TPT1)." (PMID 38559560, 2024). "Initially, we examined the expression of ITGA2 in normal pancreatic ductal epithelial cells (HPDE-C7) and pancreatic cancer cell lines PANC-1 and SW1990." (PMID 37881431, 2023). "ITGA2 is highly expressed in pancreatic cancer tissues and correlates with a decreased overall survival (OS) and disease-free survival (DFS) rate in patients with high ITGA2 expression." (PMID 36765586, 2023). "We examined the expression of ITGA2, MET, E-cadherin, PD-L1, CD4, and CD8 proteins in 62 pancreatic cancer tissue samples using multi-tissue immunofluorescence and immunohistochemistry techniques." (PMID 37881431, 2023). "The results showed that after inhibiting the expression of SDC1 and ITGA2, the EMT process of pancreatic cancer cell lines was inhibited; this was manifested by an increased expression of E-cadherin and decreased expression of N-cadherin, Snail, and Twist." (PMID 37907515, 2023). "The relationship between the expression of ITGA2, CD4 and CD8 in pancreatic cancer tissues and the clinicopathological features." (PMID 37881431, 2023). "The results showed that with the extension of inoculation time of pancreatic cancer cells, the expression levels of SDC1 and ITGA2 in tumor tissues also increased." (PMID 37907515, 2023). "In order to further comprehend the regulatory relationship between ITGA2, EMT, and PD-L1 in pancreatic cancer cells, we conducted a detection study." (PMID 37881431, 2023). "In order to further verify the expression of the ITGA2 in PDAC tissue, we collected five normal pancreatic tissues (from donors who died of cardiovascular disease) and 15 pancreatic cancer patients, and performed immunohistochemistry." (PMID 37386391, 2023). "Based on these comprehensive results, it can be concluded that ITGA2 regulates the expression of EMT markers and PD-L1 in pancreatic cancer cells." (PMID 37881431, 2023). "To verify the influence of ITGA2 and TGF-β on the morphological changes of pancreatic cancer and tumor cell progression, we conduct CCK8 test, plate cloning, flow cytometry experiments and animal experiments." (PMID 35193647, 2022). "The ITGA2 inhibited the SMAD2 expression by interacting with TFCP2 and inhibiting its nuclear translocation in the pancreatic cancer cells." (PMID 35193647, 2022).